INS (insulin)
Diseases named in the same sentence as INS in open-access papers (continued):
Sharing a sentence is not in itself a finding about the gene and the disease.
Hyperglycemia (continued). "The dissociation of insulin from these immune complexes can cause unpredictable and severe glycemic variability, including recurrent hypoglycemic episodes and intermittent hyperglycemia." (PMID 41585798, 2025). "Hyperglycemia has been associated with increased relaxation of pelvic floor muscles, while insulin resistance contributes to muscle atrophy and weakness, both of which predispose to urinary incontinence." (PMID 41295285, 2025). "This leads to the formation of a viscous cycle of hyperglycemia causing increased oxidative stress that further decreases insulin secretion, which in turn results in hyperglycemia." (PMID 39941397, 2025). "Increased protein O‐GlcNAcylation is also associated with hyperglycemia‐induced glucose toxicity, β cell apoptosis, and impaired insulin secretion." (PMID 39279604, 2025). "Remarkably, it not only demonstrated the ability to overcome resistance mediated by secondary PI3Kα mutations but also minimized the impact on insulin signaling, reducing hyperglycemia and allowing for higher target engagement and a wider therapeutic index." (PMID 41430313, 2025). "These complications are caused by increased fetal insulin production secondary to fetal hyperglycemia." (PMID 41018546, 2025). "Due to impaired insulin secretion by the pancreas, patients with pancreatitis often experience a degree of insulin deficiency, which exacerbates hyperglycemia." (PMID 40937420, 2025). "A recent article proposes that mitochondrial dysfunction in GDM increases oxidative stress and impairs the insulin signaling pathway, which would increase the risk of hyperglycemia." (PMID 40005008, 2025). "Early defects in insulin secretion lead to a loss of first‐phase insulin secretion, while fasting hyperglycemia is a later finding in CFRD." (PMID 40856269, 2025). "In contrast, other reports suggest a potential association between the use of DTG‐based regimens and an increased risk of hyperglycaemia, possibly due to its effects on insulin sensitivity and glucose metabolism." (PMID 40289329, 2025). "Some of the side effects of GCs include insulin resistance, skeletal muscle atrophy, and fat mass gain in addition to the risk of hyperglycemia." (PMID 40362449, 2025). "Hyperglycemia remains a consistent risk factor, with intensive insulin therapy demonstrating a reduction in CIP incidence, likely due to its neurotoxic effects and mitochondrial dysfunction." (PMID 41322912, 2025). "MODY comprises hyperglycaemia in young people (under 25 years of age) caused by monogenic alterations of genes responsible for beta-cell function and insulin action, representing 1–5% of diabetic cases." (PMID 40332430, 2025). "Basal hyperglycemia is caused by a lower insulin-to-glucagon ratio resulting in increased production of glucose by the liver." (PMID 39859258, 2025). "Specifically, in mice heterozygous for Kcnk16 L114P mutation, we observe neonatal hyperglycemia due to blunted glucose-stimulated insulin secretion, which can additionally result in neonatal death in mice homozygous for the mutant (L114P) allele of Kcnk16." (PMID 38700926, 2024). "The overexpression of irisin in obese mice has been linked to improved insulin sensitivity, enhanced energy expenditure, and reduced hyperlipidemia, hyperglycemia, and hypertension." (PMID 38431555, 2024). "Polyneuropathy is a micro-damage of the peripheral nerve system and caused by (chronic) hyperglycemia and altered insulin signaling." (PMID 38287984, 2024). "Elevated specific lipids with hyperglycemia, such as oleate, have been associated with lipotoxicity, contributing to insulin resistance by impairing insulin signaling pathways." (PMID 39195507, 2024). "The disease is characterized by hyperglycemia and is mainly caused by defective insulin secretion or impaired insulin bioactivity." (PMID 38568081, 2024).
Hyperglycemia (continued). "Eif2ak3–/– mice developed similar phenotypes with hyperglycemia, hypoinsulinemia, ER stress, β-cell loss, misfolded insulin, and defects in the secretory pathway causing accumulation of proinsulin in the ER." (PMID 38744890, 2024). "Taken together, these findings support the role of dietary patterns in the remodeling of gut microbiota and resulting alterations in biomarkers associated with inflammation, hyperglycemia, and insulin signaling dysregulation." (PMID 38257161, 2024). "T1DM is characterized by elevated blood glucose levels (hyperglycemia) caused by deficient insulin production due to destruction of the β-cells of the pancreatic islets of Langerhans predominantly as a result of autoimmune inflammation." (PMID 39839113, 2024). "It causes the insulin target organs to be less sensitive to insulin action, making normal levels of insulin ineffective in lowering blood glucose and leading to hyperglycemia." (PMID 39554331, 2024). "Type 1 diabetes (T1D) is an autoimmune chronic disorder that damages beta cells in the pancreatic islets of Langerhans and results in hyperglycemia due to the loss of insulin." (PMID 39735417, 2024). "Elevated C-peptide and hyperglycemia indicate that β cell function was preserved and insulin resistance is the predominant mechanism underlying hyperglycemia in COVID-19." (PMID 37934800, 2024). "This destruction of insulin-producing beta cells results in persistent hyperglycemia, which closely mimics the insulin deficiency and metabolic disturbances characteristic of type 1 diabetes." (PMID 39712809, 2024). "Since fasting hyperglycemia is associated with elevated hepatic insulin resistance, and the liver contributes approximately 25% of postprandial glucose uptake, skeletal muscle remains the primary tissue responsible for the remaining glucose disposal." (PMID 38904921, 2024). "This process leads to hyperglycemia and, at the same time, the insulin feedback pathway causes PI3K/AKT/mTOR pathway activation causing attenuation of the therapeutic response of PI3K inhibitors." (PMID 38396649, 2024). "In patients with T2DM, the oxidative stress induced by hyperglycaemia is linked to impaired insulin signalling and subsequent insulin resistance." (PMID 39458491, 2024). "PTDM has been associated with pathways involved in insulin sensitivity and/or insulin deficiency as well as pathways linked to hyperglycemia and vascular complications." (PMID 38674437, 2024). "Incidentally, this group with more advanced CKD were receiving less statin and anti-thrombotic therapy despite their high CV risk, and more insulin than metformin for their hyperglycemia." (PMID 39704168, 2024). "Both hyperglycemia and compromised cerebral insulin signaling lead to neurodegeneration, causing cognitive dysfunction and dementia." (PMID 38539672, 2024). "Findings from a preclinical study showed that Atg‐deficient mice experienced hypoinsulinemia and hyperglycaemia since; autophagy regulates intracellular content and the release of insulin from pancreatic β cells." (PMID 39656379, 2024). "Both impaired β-cell secretory capacity and reduced insulin sensitivity have been implicated in the persistence of impaired glucose metabolism following stress hyperglycemia." (PMID 37934800, 2024). "Reduced HRV in T2DM patients has been associated with age, HbA1c levels, hyperglycemia, serum insulin levels, as well as the development of hepatic steatosis." (PMID 39596529, 2024). "Animal models have shown that vitamin D deficiency directly reduces the pancreas' insulin secretion in response to hyperglycemia." (PMID 39845452, 2024). "These are often only possible in open-source HCLS research frameworks today, but in the future will mark a significant leap toward individualized care, enabling more precise insulin dosing and reducing the risks associated with hyperglycemia and hypoglycemia." (PMID 38337523, 2024).
Hyperglycemia (continued). "Hyperglycemia, a complicated metabolic disease associated with DM, frequently results from issues with insulin secretion or metabolism, or perhaps both." (PMID 38603728, 2024). "In the current study, a low-dose streptozotocin-induced T2DM model exhibited typical symptoms including body weight loss, hyperglycemia, decreased insulin, and insulin resistance, consistent with previous studies." (PMID 38509482, 2024). "Therapy for DM in dogs currently involves a symptomatic approach by administering lifelong exogenous insulin to control hyperglycemia and prevent associated complications, along with proper dietary management and exercise." (PMID 39195834, 2024). "Glucocorticoids cause hyperglycemia by disrupting various physiological metabolic mechanisms through increased insulin resistance and decreased insulin secretion." (PMID 39249163, 2024). "IR refers to the decreased response of tissue cells to insulin, leading to the inability of insulin to effectively promote the uptake and utilization of glucose and then causing the occurrence of hyperglycemia." (PMID 39220593, 2024). "Previous studies have found that caffeine can induce thermogenesis and weight loss, thus improving insulin sensitivity and glucose-induced insulin secretion, preventing hyperglycemia and oxidative stress." (PMID 39061109, 2024). "The exact mechanism by which steroids cause hyperglycemia is not fully understood, but it is believed to involve a combination of decreased insulin sensitivity, increased hepatic glucose production, and impaired glucose uptake in peripheral tissues." (PMID 38510914, 2024). "We observed early-onset diabetes characterized by hyperglycemia, reduced serum insulin levels, β-cell loss, increased pancreatic lipases and pro-inflammatory cytokines, and the progression of metabolic dysfunction." (PMID 38744890, 2024). "We previously demonstrated that ER hyperoxidation impairs proinsulin trafficking, leading to a loss of insulin secretory granules in models of hyperglycemia and β cell dysfunction." (PMID 38935435, 2024). "Insulin is a hormone that plays a vital role in regulating blood glucose levels, and its absence leads to hyperglycemia, a hallmark of diabetes." (PMID 39203886, 2024). "Studies in rabbits and mice demonstrate a clear causal role for hyperglycemia decreasing leukocyte phagocytosis that is restored with insulin." (PMID 39234180, 2024). "If the fetus carries the mutation, moderate maternal hyperglycemia is beneficial, as it promotes fetal insulin secretion in the fetus and prevents intra-uterine growth retardation." (PMID 38745742, 2024). "Recently, experiments on Sprague Dawley rats and lean Zucker rats confirmed that acute AVP administration causes hyperglycemia, mediated by V1aR receptors, and that this is followed by secretion of insulin and a decrease in blood glucose level." (PMID 39769071, 2024). "The perioperative hyperglycemia with the need for insulin therapy before hospital discharge was associated with PTDM diagnosis." (PMID 38352660, 2024). "First, our institution had already implemented many strategies to ensure insulin safety; it is possible that prior safety work enhanced overall insulin safety and awareness of insulin as a high-risk drug, thereby improving hyperglycemia and hypoglycemia rates." (PMID 38324312, 2024). "These devices measure the glucose concentration in interstitial fluid and allow users to better manage their insulin intake or menu choices, which reduces the risk of hypoglycemia or hyperglycemia." (PMID 39590019, 2024). "The early morning transient hyperglycemia appears to be due to an increase in glycogenolysis and gluconeogenesis associated with inadequate insulin secretion, sub-optimal insulin action, or insulin resistance." (PMID 38316854, 2024).
Hyperglycemia (continued). "Especially post-prandial glucose (PPG) measurements are important, as pasireotide-associated hyperglycemia is related to decreases in glucose-stimulated insulin secretion and incretin hormone response which should be most evident after a meal." (PMID 38405148, 2024). "There is a higher risk of developing hyperglycaemia for women in whom insulin secretion is inadequate, or those with higher peripheral insulin resistance." (PMID 37022834, 2024). "It is characterized by progressive autoimmune β-cell destruction, driven by autoantibodies that rapidly result in insulin deficiency, hyperglycemia, and a dependence on exogenous insulin." (PMID 39683465, 2024). "Excessive glucocorticoid can promote gluconeogenesis, inhibit insulin, reduce glucose tolerance and cause hyperglycemia." (PMID 38496026, 2024). "Age-associated impaired insulin secretion is characterized by reduced β-cell sensitivity and impaired insulin response to hyperglycemia." (PMID 38794702, 2024). "The disease is characterized by loss of sensitivity to insulin-producing β cells, which leads to β cell destruction, a decline in endogenous insulin secretion and, consequently, hyperglycemia." (PMID 38902652, 2024). "It manifests as a syndrome characterized by hyperglycemia, which can arise from one or both causative factors—defects in insulin secretion and defects in insulin sensitivity within target tissues." (PMID 39605770, 2024). "Isolated fasting hyperglycemia implies insulin deficiency and hepatic insulin resistance but with normal muscle insulin sensitivity." (PMID 39110713, 2024). "An exception to this is alpelisib, a PI3K inhibitor that carries a boxed warning for hyperglycemia caused by inhibition of intracellular response to insulin." (PMID 39088060, 2024). "Previous studies have shown that insulin secretion-associated hyperglycemia can be involved in the pathogenesis of DKD via multiple pathways including the polyol pathway." (PMID 39457682, 2024). "Hyperglycemia induces a proinflammatory milieu and cytokine imbalance, resulting in placental vascular alterations, whilst insulin directly causes placental inflammation." (PMID 38486097, 2024). "Hyperglycemia is associated with the impairment in insulin excretion with extreme hepatic glycogenolysis and gluconeogenesis; and reduction uptake of glucose by the tissues." (PMID 38528644, 2024). "This breakdown in immune homeostasis or ‘tolerance’ leads to β‐cell destruction, resulting in insulin (INS) deficiency, hyperglycaemia and the lifelong necessity for INS supplementation in afflicted individuals." (PMID 39702941, 2024). "Heterozygous NEUROD1 mutations can disrupt insulin synthesis, impair endocrine pancreas cell maturation, and lead to hyperglycemia (MODY6)." (PMID 39264012, 2024). "Guidelines also suggest the use of insulin in cases of ongoing catabolism (weight loss), if symptoms of hyperglycaemia are present or when HbA1c or blood glucose levels are very high." (PMID 38679644, 2024). "STZ, a toxin derived from Streptomyces bacteria, targets explicitly and damages insulin-producing β cells in the pancreas, resulting in insulin deficiency and hyperglycaemia, which simulates type 1 diabetes in humans." (PMID 39204115, 2024). "Chronic hyperglycemia is a potent inducer of free radical production, leading to oxidized insulin variants." (PMID 39378614, 2024). "The following are the two most significant causes of hyperglycemia: age-related declines in insulin production and increased insulin resistance caused by changes in body composition and sarcopenia." (PMID 38817391, 2024). "The biochemical signals between cells of different tissues such as the pancreas, liver, fat, and skeletal muscle by glucagon and insulin are likely candidates responsible for hyperglycemia and the loss of antagonism by the single-node inhibitors." (PMID 39456616, 2024).
Hyperglycemia (continued). "Under normal conditions, AVP exerts direct metabolic actions in the liver, causing hyperglycemia; however, it also increases release of insulin, which counteracts the hyperglycemic effect and helps restore plasma glucose level to the normal values." (PMID 39769071, 2024). "The hallmark symptom is hyperglycemia, which lasts for an extended period of time and can be caused by either inadequate insulin synthesis or impaired insulin action." (PMID 39063997, 2024). "Mouse studies have indicated that increased c-Kit expression leads to increased insulin secretion, so it would follow that c-Kit inhibition would more likely cause hyperglycemia than hypoglycemia." (PMID 39659385, 2024). "The resulting destruction of β-cells reduces or entirely depletes insulin, thereby causing hyperglycemia." (PMID 39598390, 2024). "Since pancreatic β cells produce insulin, their obliteration leads to insulin deficiency and consequently to hyperglycemia." (PMID 38892159, 2024). "Premenopausal female mice are protected from β-cell apoptosis and hyperglycemia, but male mice develop insulin-deficient diabetes." (PMID 39337631, 2024). "As insulin doses are reduced to prevent hypoglycemia, there is also a potential risk of hyperglycemia and eliciting diabetic ketoacidosis." (PMID 39906033, 2024). "Due to the individual variability and complex glucose dynamics, optimizing the doses of insulin delivery to minimize the risk of hyperglycemia and hypoglycemia is still a challenge in both CGM and intermittent fingerstick glucose monitoring." (PMID 37022834, 2024). "This is because IR increases during GDM, and the insulin secreted by the islet β cells cannot meet the demand, causing the occurrence of hyperglycemia." (PMID 39220593, 2024). "Findings indicate that more severe GDM, measured by either clinical markers assessing degree of hyperglycemia or need for insulin treatment, predicts risk of developing T2D." (PMID 38216688, 2024). "The perioperative hyperglycemia with the need for treatment with insulin before hospital discharge was associated with PTDM." (PMID 38352660, 2024). "In the prediabetic state, insulinemia increases in order to meet normal insulin requirements, which leads to chronic hyperinsulinemia and hyperglycemia caused by β-cell failure, and the final stage is represented by the appearance of T2DM." (PMID 39768947, 2024). "A close correlation was observed between hyperglycemia, reduced serum insulin levels, loss of β-cell mass, and metabolic disorders in BI-1-deficient mice, resembling early-onset diabetes." (PMID 38744890, 2024). "Chronic hyperglycemia triggers oxidative stress and the generation of reactive oxygen species (ROS), leading to oxidized insulin variants." (PMID 39378614, 2024). "Upon endocrine evaluation, she was found to have generalized loss of adiposity, hypoleptinemia, and persistent hyperglycemia despite aggressive insulin administration." (PMID 38314238, 2024). "In mice, B cell-specific deletion of the Rictor gene (an important component of mTORC2) is associated with reduced plasma insulin levels due to decreased insulin secretion from islets, leading to hyperglycemia." (PMID 39346923, 2024). "In turn, the efficacy of ATP-dependent pathways essential to the release, secretion, and functioning of insulin gets affected due to the altered energy balance that is caused by hyperglycemia." (PMID 39674630, 2024). "Quantifying the insulin requirement is essential for tailoring insulin therapy to each patient's needs while minimizing the risk of hyperglycemia or hypoglycemia." (PMID 38510914, 2024). "This latter event caused the participant to disconnect their insulin pump and leave it outside of the testing room, reportedly resulting in the student experiencing hyperglycemia and difficulty focusing on the exam." (PMID 38889174, 2024). "This condition is associated with elevated levels of insulin, leading to compensatory hyperinsulinemia and fasting hyperglycemia.." (PMID 38658944, 2024).